SMARCB1 (SWI/SNF related BAF chromatin remodeling complex subunit B1)
Diseases named in the same sentence as SMARCB1 in open-access papers (continued):
Sharing a sentence is not in itself a finding about the gene and the disease.
schwannomatosis (continued). "In patients with SMARCB1-related schwannomatosis, the increased malignancy risk must be considered which may contribute to reduced life expectancy (Sect." (PMID 40794298, 2025). "Notably, individuals with the SMARCB1 pathogenic variant have an increased risk of developing schwannomatosis." (PMID 39170644, 2024). "Additionally, schwannomas and neurofibromas are tightly linked with genetic conditions such as neurofibromatosis type 1 (NF1) and NF2, with schwannomatosis emerging as a separate syndrome associated with SMARCB1 mutations." (PMID 39001422, 2024). "In addition, a recent deep massive parallel sequencing study of 35 schwannomatosis cases reported two novel deep intronic variants in intron 4 of SMARCB1 (NM_003073.5:c.500+883T>G and NM_003073.5:c.500+887G>A)." (PMID 35723634, 2022). "Conversely, a CSS-causing mutation in SMARCB1 exon 9 can predispose to schwannomatosis." (PMID 31273213, 2019). "However, the frequency of somatic mosaicism of SMARCB1 or LZTR1 mutations in patients with schwannomatosis is as yet unclear." (PMID 29779243, 2018). "Germline mutations in SMARCB1 also cause schwannomatosis (OMIM #162091)." (PMID 29779243, 2018). "It is known that germline SMARCB1 mutations may cause rhabdoid tumor predisposition syndrome (RTPS1) or schwannomatosis." (PMID 29779243, 2018). "So far, two schwannomatosis predisposition genes have been identified, SMARCB1 and LZTR1." (PMID 27921248, 2017). "The leiomyosarcoma and the pRCC1 observed in two patients with SMARCB1 mutation-positive schwannomatosis indicate that malignancy may, indeed, occur in a subset of patients." (PMID 27921248, 2017). "Consequently, the mosaic SMARCB1 expression is most likely related to the hypomorphic nature of the mutations in schwannomatosis patients that encode stable mRNA transcripts giving rise to detectable amounts of SMARCB1 protein." (PMID 27921248, 2017). "The existence of a specific developmental time window could also explain the presence of RTs and schwannomatosis within a family sharing the same SMARCB1 mutation." (PMID 28824165, 2017). "A cyclin D1 repression assay has shown that mutant SMARCB1 proteins, derived from expression plasmids harbouring the same missense and splice-site mutations noted in patients with schwannomatosis, were capable of suppressing cyclin D1 activity in a similar manner to the wild-type SMARCB1 protein." (PMID 27921248, 2017). "A risk of malignancy may exist in those schwannomatosis patients with SMARCB1 germline mutations that are less likely to be hypomorphic." (PMID 27921248, 2017). "Although biallelic mutations of SMARCB1 or LZTR1 have been detected in the tumours of patients with schwannomatosis, the classical two-hit model of tumorigenesis is insufficient to account for schwannoma growth, since NF2 is also frequently inactivated in these tumours." (PMID 27921248, 2017). "The SMARCB1 gene has been found to be mutated in schwannomatosis patients." (PMID 22567403, 2012). "INI1/SMARCB1 immunostaining may show mosaic loss in PS associated with schwannomatosis." (PMID 41209860, 2025). "Furthermore, functional characterization of known causative variants for schwannomatosis will undoubtedly advance our understanding of potentially new mechanisms of disease in schwannomatosis, particularly for variants located in noncoding regions of both SMARCB1 and LZTR1." (PMID 35723634, 2022). "Thus, we tested the hypothesis that NF2 loss is necessary for schwannoma formation in schwannomatosis patients with germline SMARCB1 mutations." (PMID 28824165, 2017). "Similarly, both loss of function and missense mutations in SMARCB1 can lead to schwannomatosis, and it still remains unclear why some carriers develop schwannomas, while other develop RTs." (PMID 27866340, 2017).
schwannomatosis (continued). "By inducing Smarcb1 loss at later developmental stage in the Schwann cell lineage, in addition to biallelic Nf2 gene inactivation, we generated the first mouse model developing schwannomas with the same underlying gene mutations found in schwannomatosis patients." (PMID 28824165, 2017). "Germline mutations in the SMARCB1 gene are implicated in both infantile ATRT and adult schwannomatosis, although the two conditions differ in mutation type, tumor phenotype, clinical behavior, and penetrance." (PMID 41514521, 2025). "A common pattern observed in these families was that the parent who carried the SMARCB1 PV had schwannomatosis whereas their offspring had MRT." (PMID 40794298, 2025). "This patient with a germline SMARCB1 mutation and confirmed CSS diagnosis developed schwannomatosis." (PMID 39170644, 2024). "Although mutations in SMARCB1 are observed in both CSS and schwannomatosis, the literature notes one previous case of an individual with a SMARCB1 mutation diagnosed with CSS and schwannomatosis." (PMID 39170644, 2024). "Mutations of the SMARCB1 protein subunit of the BAF complex are implicated in both CSS and schwannomatosis." (PMID 39170644, 2024). "This case report discusses the clinical presentation, imaging, and pathology of a patient who presents with schwannomatosis and a diagnosis of CSS with a SMARCB1 mutation." (PMID 39170644, 2024). "SWN is a clinical distinct entity as a result of germline NF2 (22q-related schwannomatosis), or SMARCB1 (SMARCB1-related schwannomatosis), or LZTR1 variant (LZTR1-related schwannomatosis), which are located centromeric to NF2 on chromosome 22." (PMID 37046591, 2023). "ULs can be associated with tumor predisposition syndromes, including HLRCC, Cowden syndrome, and Schwannomatosis, caused by germline mutations in FH, PTEN, and SMARCB1, respectively." (PMID 36773604, 2023). "Multiple tumors are a hallmark of neurofibromatosis type 1(NF1) and related forms, NF2-related-schwannomatosis (formerly NF2) or SMARCB1/LZTR1-related schwannomatoses." (PMID 35741273, 2022). "Seven years after identification of SMARCB1 as a causal entity, a second 22q gene LZTR1 was identified as a cause of schwannomatosis." (PMID 35361920, 2022). "The gene was also linked in at least some families to a tendency to develop meningiomas, although this tumour is still relatively uncommon even in SMARCB1-related schwannomatosis." (PMID 35361920, 2022). "It is, however, closely related to schwannomatosis, due to variants in either INI1 (SMARCB1) or LZTR1, which are closely located to NF2 on chromosome 22." (PMID 33445724, 2021). "SMARCB1 germline PVs are responsible for about 40% of inherited “schwannomatosis” and 10% of apparently sporadic cases, characterized by the development of multiple indolent schwannomas." (PMID 33532948, 2021). "Spinal schwannomas, increased severity of pain and reduced penetrance were seen more commonly in LZTR1‐related schwannomatosis than in SMARCB1‐related tumors." (PMID 33269527, 2021). "Another substantial number of cases of CSS are due to missense PV in the last 2 exons of SMARCB1, quite similar to those reported in schwannomatosis." (PMID 33532948, 2021). "Consistently, a patient with CSS affected by schwannomatosis and a missense PV in SMARCB1 has been reported." (PMID 33532948, 2021). "Multiple meningiomas occur in 5% of schwannomatosis cases, but only in association with SMARCB1 mutations, hinting at a potential interaction between NF2 and SMARCB1 in meningioma pathogenesis, later validated in NGS studies." (PMID 31652973, 2019). "Instead, germline mutations of either the SMARCB1 or LZTR1 tumour suppressor genes have been identified in 86% of familial and 40% of sporadic schwannomatosis patients." (PMID 27921248, 2017).
schwannomatosis (continued). "Although the exact molecular pathogenetic mechanisms in these schwannomas remain to be elucidated, a 4-hit/3-step mechanism involving SMARCB1 and NF2 genes seems to underlie development of these benign tumors in schwannomatosis patients." (PMID 28824165, 2017). "Biallelic inactivation of SMARCB1 has been observed in both schwannomas and meningiomas of patients with schwannomatosis." (PMID 27921248, 2017). "Schwann cells dissociated from the sciatic nerve of SMARCB1/INI1 knockout mice have been used as an in vitro model of schwannomatosis." (PMID 26657314, 2015). "We also compared SMARCB1 levels in the parental schwannomatosis tumors with those in tumors isolated from patients with other types of nerve sheath tumors." (PMID 26657314, 2015). "Still, SMARCB1 levels were similar between the parent tumors and the corresponding schwannomatosis cell lines, further supporting retention of phenotype." (PMID 26657314, 2015). "Both schwannomatosis–related tumors exhibited a significantly lower level of SMARCB1 expression, as compared to tumors isolated from patients with either single schwannomas or neurofibromas." (PMID 26657314, 2015). "The SMARCB1 gene has been found to harbor germline alterations in both familial and sporadic schwannomatosis patients, with a greater number of spinal schwannomas in familial cases and the presence of meningiomas although this latter point remains debated." (PMID 21255467, 2011). "However, people with LZTR1-related schwannomatosis can have unilateral vestibular schwannomas and people with SMARCB1-related schwannomatosis can develope meningiomas." (PMID 40510571, 2025). "An association between specific pathogenic SMARCB1 variants and the occurrence of MPNSTs in schwannomatosis patients has not been identified." (PMID 40794298, 2025). "Segmental schwannomatosis has been seen in approximately one third of non-NF2-related schwannomatosis, but these cases have not generally been associated with identifiable SMARCB1 or LZTR1 mosaic variants." (PMID 41284083, 2025). "In addition to SMARCB1 and LZTR1, other schwannomatosis predisposition genes located on chromosome 22q are likely to exist." (PMID 40794298, 2025). "Additionally, germline SMARCB1 PVs have been identified in patients with conditions as clinically diverse as Rhabdoid Tumour Predisposition Syndrome type 1 (RTPS1), schwannomatosis and neurodevelopmental disorders such as Coffin-Siris syndrome (CSS)." (PMID 40794298, 2025). "By contrast, SMARCB1 mutations reported in schwannomatosis are primarily non-truncating, missense or splice-site mutations and in-frame deletions, thus probably leading to mutant protein with residual function." (PMID 39471843, 2024). "The study also has implications for radiation treatments in other tumor predisposition syndromes, beyond NF1 where a high-risk of MPNST and high-grade glioma is already known after childhood irradiation, and especially for SMARCB1-related-schwannomatosis in which MPNST is already reported." (PMID 37051330, 2023). "Interestingly, schwannomatosis and cribriform neuroepithelial tumor have also been found to have alterations in SMARCB1, but overall outcomes remain high." (PMID 35892904, 2022). "There is also a possibility that at least a proportion of the schwannomatosis cases that remain genetically unexplained might be caused by a variant within NF2, SMARCB1, or LZTR1 that has been missed by routine diagnostic methods." (PMID 35723634, 2022). "Analysis of SMARCB1 variant-negative schwannomatosis patients led to the discovery of LZTR1 variants in 2014." (PMID 35698239, 2022). "The most common schwannomatosis‐associated gene is NF2, but SMARCB1 and LZTR1 are also associated." (PMID 35723634, 2022).
schwannomatosis (continued). "It is of interest that few variants associated with SMARCB1 related schwannomatosis have been associated with meningioma risk and overall the chances of developing meningioma in SMARCB1 related schwannomatosis without these specific missense variants is low." (PMID 33262459, 2021). "Unlike the germline SMARCB1 mutations detected in RT cases, schwannomatosis-associated alterations determine reduced expression levels or a partial loss of function of the SMARCB1 protein." (PMID 33692948, 2021). "The molecular mechanisms by which inactivation of the LZTR1 or SMARCB1/INI1 gene in addition to the NF2 gene causes schwannomatosis are not understood." (PMID 34604034, 2021). "Unlike NF2, schwannomatosis patients with germline loss of SMARCB1 have a higher risk of developing MPNSTs." (PMID 34604034, 2021). "Schwannomatosis is associated with a nontruncating mutation at the beginning of end of the SMARCB1 gene, presenting as a bening tumor disposition syndrome; 5% of patients with this syndrome will develop a meningioma." (PMID 33194703, 2020). "Differential diagnosis of schwannomatosis can be difficult in patients, especially if they are oligosymptomatic and testing for SMARCB1 and LZTR1 germline mutations is negative." (PMID 32443592, 2020). "Rarely, the presence of multiple meningiomas may be associated with other syndromes resulting from alterations in SUFU, SMARCE1, and SMARCB1 (schwannomatosis)." (PMID 31161239, 2020). "Finally, in schwannomatosis, the mutated gene of interest, INI1/SMARCB1, encodes a subunit of the SWI/SNF protein complexes that is known to function in chromatin remodeling." (PMID 31450674, 2019). "In this study, we analyzed the SMARCB1 deletion segregating in the family of patient II.4 in greater detail and report on the subsequent course of the disease in patient II.4 who was diagnosed with schwannomatosis at the age of 21 years." (PMID 29779243, 2018). "Patient 7, a 75 year old man with esophageal cancer and no family history of note, was found to have a germline SMARCB1 variant (c.143C > T; p.Pro48Leu), which has been associated with schwannomatosis and multiple meningiomas." (PMID 30092803, 2018). "Similar to schwannomatosis patients, loss of both Smarcb1 and Nf2 does not increase the malignancy of mGFAP-Cre;Smarcb1flox/flox;Nf2flox/flox tumors compared to mGFAP-Cre;Nf2flox/flox tumors with single Nf2 loss." (PMID 28824165, 2017). "Taken together, we surmise that it is unlikely that unidentified somatic mosaicism for SMARCB1 or LZTR1 mutations would account for the high number of sporadic schwannomatosis cases without identified mutations." (PMID 27921248, 2017). "However, one patient with a SMARCB1 mutation and CSS has been reported to develop schwannomatosis, another type of tumour caused by germline SMARCB1 mutations." (PMID 27866340, 2017). "Mosaicism for somatic LZTR1 or SMARCB1 mutations in patients with schwannomatosis has not so far been reported and only one case of germline (gonadal) mosaicism for a SMARCB1 mutation has been identified." (PMID 27921248, 2017). "This 4-hit/3-step model of tumorigenesis probably also holds true for other benign tumours observed in patients with SMARCB1-positive schwannomatosis, since biallelic inactivation of SMARCB1 and NF2 has been observed in a meningioma and leiomyoma of patients with germline SMARCB1 mutations." (PMID 27921248, 2017). "Germline mutations in LZTR1, a gene closely linked to NF2 and SMARCB1 on chromosome 22, have recently been identified in a significant proportion of schwannomatosis patients lacking SMARCB1 germline mutations." (PMID 28824165, 2017). "Such a high rate of LZTR1 mutation in SMARCB1 mutation-negative schwannomatosis patients was not, however, observed in subsequent studies." (PMID 27921248, 2017).
schwannomatosis (continued). "By contrast, mitotic recombination accounts for 19% of the LOH events in NF2-associated schwannomas (14 of 72 schwannomas analysed) and 23% (5/22) of schwannomas from schwannomatosis patients without germline SMARCB1 mutations." (PMID 27921248, 2017). "Although the 4-hit/3-step model accounts for the majority of the tumours in the cases of SMARCB1 mutation-positive schwannomatosis, biallelic inactivation of the NF2 gene is not observed in all schwannomas." (PMID 27921248, 2017). "A new gene, LZTR1, located at 22q11.21 and centromeric to SMARCB1 has been recently reported to be mutated in ~80% of Schwannomatosis patients negative for SMARCB1 mutation." (PMID 25739810, 2015). "Similar to the situation in schwannomatosis patients, the loss of both Smarcb1 and Nf2 did not increase the malignancy of the tumours in mGFAP-Cre; Smarcb1flox/flox;Nf2flox/flox mice as compared to tumours in mGFAP-Cre; Nf2flox/flox mice with biallelic Nf2 loss but retention of Smarcb1 activity." (PMID 40794298, 2025). "However, it can also present as multiple lesions, particularly in association with syndromes such as neurofibromatosis type-2 and schwannomatosis, which are linked to genetic mutations in the NF2 gene and the tumor suppressor genes SMARCB1 and LZTR1, respectively." (PMID 40575212, 2025). "Furthermore, many sporadically affected individuals that do not have either LZTR1 or SMARCB1 germline pathogenic variants but meet schwannomatosis criteria, have mosaic NF2 with identical pathogenic variants in two separate schwannomas." (PMID 35361920, 2022). "However, some patients with schwannomatosis do not have LZTR1 or SNF5/SMARCB1/INI1 mutations, suggesting the presence of another tumor suppressor gene on chromosome 22q in schwannomatosis development." (PMID 34604034, 2021). "Furthermore schwannomatosis predisposition genes are likely to exist since germline mutations in SMARCB1 or LZTR1 are not detectable in at least 50% of sporadic patients with schwannomatosis (Kehrer‐Sawatzki, Farschtschi, Mautner, & Cooper, 2017)." (PMID 29779243, 2018). "Furthermore, SMARCB1 germline mutations have not been found in patients with multiple meningiomas in the absence of schwannomatosis." (PMID 27921248, 2017). "Alternatively, somatic mosaicism for SMARCB1 or LZTR1 mutations could be responsible for the relatively high proportion of sporadic schwannomatosis patients without detectable germline SMARCB1 and LZTR1 mutations." (PMID 27921248, 2017). "The three major schwannomatosis genes, NF2, LZTR1 and SMARCB1, are all located within approximately 9 megabases on chromosome 22 and cause three genetically distinct conditions with significant clinical phenotypic overlap." (PMID 41284083, 2025). "RTPS1 is characterized by the occurrence of highly malignant atypical teratoid rhabdoid tumours (AT/RT) affecting mostly infants, whereas SMARCB1-related schwannomatosis is generally diagnosed after the age of 30 and is characterized by benign schwannomas." (PMID 40794298, 2025). "Exploration of the possible interactions of potential candidate genes for schwannomatosis with the known causative genes, might provide some insight into the type and location of novel PVs in cases where no variants in SMARCB1, LZTR1, or NF2 have been identified." (PMID 35723634, 2022). "SMARCB1-associated lesions may be particularly problematic, although typically bilateral vestibular schwannomas and ependymomas are not typically identified in schwannomatosis patients." (PMID 31161239, 2020).